CHRNA2 (cholinergic receptor nicotinic alpha 2 subunit)
Description:
Component of neuronal acetylcholine receptors (nAChRs) that function as pentameric, ligand-gated cation channels with high calcium permeability among other activities. nAChRs are excitatory neurotrasnmitter receptors formed by a collection of nAChR subunits known to mediate synaptic transmission in the nervous system and the neuromuscular junction. Each nAchR subunit confers differential attributes to channel properties, including activation, deactivation and desensitization kinetics, pH sensitivity, cation permeability, and binding to allosteric modulators. CHRNA2 forms heteropentameric neuronal acetylcholine receptors with CHRNB2 and CHRNB4 and plays a role in nicotine dependence.
Tractability: Small molecule: a structure with a bound ligand is known; a high-quality ligand is known; it belongs to a druggable protein family. Antibody: its Gene Ontology location is reachable by antibodies, with high confidence; UniProt places it where antibodies can reach, with medium confidence; UniProt predicts a signal peptide or a membrane-spanning region; the Human Protein Atlas places it where antibodies can reach. PROTAC: a small molecule that binds it is known.
Gene: Protein-coding gene on chromosome 8 (27,459,756 to 27,479,883, reverse strand). Ensembl gene ENSG00000120903.
Subcellular location: Synaptic cell membrane; Cell membrane
Subcellular location (Human Protein Atlas): Plasma membrane; Cytokinetic bridge; Nucleoplasm
Pathways (Reactome):
Neuronal System: Highly calcium permeable nicotinic acetylcholine receptors; Highly calcium permeable postsynaptic nicotinic acetylcholine receptors
Gene Ontology:
Molecular function: acetylcholine receptor activity; acetylcholine-gated monoatomic cation-selective channel activity; neurotransmitter receptor activity; extracellular ligand-gated monoatomic ion channel activity; heterocyclic compound binding; monoatomic ion channel activity; quaternary ammonium group binding; transmembrane signaling receptor activity
Biological process: acetylcholine receptor signaling pathway; signal transduction; calcium ion transport; membrane depolarization; monoatomic ion transmembrane transport; monoatomic ion transport; neuromuscular synaptic transmission; presynaptic modulation of chemical synaptic transmission; response to nicotine; synaptic transmission, cholinergic; cellular response to nicotine; chemical synaptic transmission, postsynaptic; excitatory postsynaptic potential; modulation of inhibitory postsynaptic potential; regulation of postsynaptic membrane potential; response to acetylcholine
Cellular component: acetylcholine-gated channel complex; plasma membrane; synapse; membrane; neuron projection; synaptic membrane; cell periphery; neuron projection cytoplasm; postsynaptic membrane; presynapse; protein-containing complex
Genetic constraint (gnomAD): Loss-of-function variants: 38 observed, 41.68 expected, observed/expected ratio (o/e) 0.91, 90% interval 0.7 to 1.2. The upper end of that interval is the gene's LOEUF score, 1.2, which puts it in group 5 of 6, group 1 being the genes least tolerant of losing a copy. Missense variants: 654 observed, 720.12 expected, observed/expected ratio (o/e) 0.91, 90% interval 0.85 to 0.97. Synonymous variants: 301 observed, 309.71 expected, observed/expected ratio (o/e) 0.97, 90% interval 0.88 to 1.07.
Gene-disease validity (ClinGen):
ClinGen rates the evidence that CHRNA2 causes each of these diseases.
familial sleep-related hypermotor epilepsy (autosomal dominant): Limited. An instance of sleep-related hypermotor epilepsy that is caused by an inherited genomic modification in an individual.
benign familial infantile epilepsy (autosomal dominant): Disputed. A genetic epileptic syndrome characterized by the occurrence of afebrile repeated seizures in healthy infants, between the third and eighth month of life.
Homologues: Orthologues: chimpanzee CHRNA2 (99% identical), macaque CHRNA2 (97% identical), dog CHRNA2 (84% identical), rabbit CHRNA2 (84% identical), pig CHRNA2 (83% identical), guinea pig CHRNA2 (83% identical), mouse Chrna2 (82% identical), rat Chrna2 (81% identical), tropical clawed frog chrna2 (69% identical), zebrafish chrna2a (68% identical), zebrafish chrna2b (67% identical). Paralogues in human: CHRNA4 (65% identical), CHRNA3 (51% identical), CHRNA6 (49% identical), CHRNB3 (46% identical), CHRNA5 (44% identical), CHRNB2 (44% identical), CHRNB4 (43% identical), CHRNA1 (41% identical), CHRNA7 (36% identical), CHRNB1 (35% identical), CHRND (34% identical), CHRNG (32% identical), and 33 more.
Diseases named in the same sentence as CHRNA2 in open-access papers:
CHRNA2 is named in the same sentence as 34 diseases in open-access papers, as found by Europe PMC text mining. Sharing a sentence is not in itself a finding about the gene and the disease. The quoted sentences say what the papers report.
epilepsy (10 papers, 2011 to 2025). A brain disorder characterized by episodes of abnormally increased neuronal discharge resulting in transient episodes of sensory or motor neurological dysfunction, or psychic dysfunction. "In this report, we expanded the spectrum of existing variations in the CHRNA2 gene contributing and associated with the development of epilepsy with the important and novel causative genetic variant." (PMID 39834405, 2025). "Among the exceptions is CHRNA2, a gene expressed in the human brain starting at birth that has been implicated in epilepsy." (PMID 33113372, 2020). "All 20 of the inherited human epilepsy-associated genes and both mouse model genes were analyzed at least once in all four of the test breeds, except for CHRNA2 in the Vizslas." (PMID 21518446, 2011). "All of the human epilepsy-associated genes, with the exception of CHRNA2, and both of the mouse model genes were excluded." (PMID 21518446, 2011). "In addition to CHRNA7, several nAChR genes have been implicated in seizure disorders including CHRNA2, CHRNA4, CHRNB2." (PMID 40880366, 2025). "The critical implication of the cholinergic system in sleep-related epilepsy was further suggested by the identification of a mutation on CHRNA2, giving the non-synonymous substitution Ile279Asn, linked to a familial epilepsy with nocturnal wandering and ictal fear." (PMID 33255633, 2020). "Hence, it is important to determine whether CHRNA2 mutations can be a significant etiologic factor in sleep-related hypermotor epilepsy, and what is the prevalent pathogenetic mechanism." (PMID 30809122, 2019). "Nine genes, two of which are human epilepsy-associated genes (GABRD and CHRNA2), had markers with heterozygosities falling below the 0.3 cut-off, prohibiting the drawing of conclusions about these genes." (PMID 21518446, 2011).
schizophrenia (5 papers, 2012 to 2023). A major psychotic disorder characterized by abnormalities in the perception or expression of reality. "For example, NAGA and CHRNA2 were reported to be associated with schizophrenia by three and seven research papers in the PubMed database, respectively." (PMID 35412455, 2022). "ENST00000407991 of CHRNA2 was significantly associated with schizophrenia only in Brain-Cerebellum, while ENST00000396398 of NAGA was significantly associated with schizophrenia in all the five optimized brain regions." (PMID 35412455, 2022). "For example, CHRNA2 is a co-acting target of smoking behavior and schizophrenia." (PMID 37817127, 2023).
autosomal dominant nocturnal frontal lobe epilepsy (4 papers, 2015 to 2022). A seizure disorder characterized by intermittent dystonia and/or choreoathetoid movements that occur during sleep. "Fast ionotropic nicotinic acetylcholine receptor (nAChR) subunit genes, α2 (Chrna2), α4 (Chrna4) and β2 (Chrnb2), have been affiliated with autosomal dominant nocturnal frontal lobe epilepsy (ADNFLE) when mutated." (PMID 28825447, 2017). "Autosomal dominant nocturnal frontal lobe epilepsy (ADNFLE) is caused by mutations in the CHRNA4, CHRNA2, CHRNB2, or KCNT1(Slack) genes." (PMID 25784856, 2015).
Obesity (4 papers, 2021 to 2024). Accumulation of substantial excess body fat. "In cluster B, we observe that CHRNA2 (cholinergic receptor nicotinic alpha 2) is expressed at significant levels in subcutaneous adipocytes, and one of its forms might be a risk factor for obesity in Koreans." (PMID 33805313, 2021).
lung carcinoma (3 papers, 2019 to 2020). "The study identified RNASET2, SECISBP2L,NRG1, CHRNA2, OFBC1 and RTEL1 as candidate genes associatedwith lung cancer." (PMID 33959694, 2020). "This study highlighted the genetic heterogeneity across histological subtypes of lung cancer and reported novel loci for lung cancer at 1p31.1 (rs71658797, FUBP1), 6q27 (rs6920364, RNASET2), 8p21.1 (rs11780471, CHRNA2), and 15q21.1 (rs66759488, SEMA6D)." (PMID 31069257, 2019).
nicotine dependence (3 papers, 2018 to 2023). Physical and psychological dependence on nicotine. "The CHRNA2 gene in chromosome 8 has recently been identified as one of the risk loci for both smoking behavior and nicotine dependence." (PMID 37626860, 2023). "CHRNA2 is a widely expressed subunit of nicotinic acetylcholine receptors, and is involved in neurocognitive disorders and nicotine dependence." (PMID 36009493, 2022). "The risk of developing nicotine addiction has been associated with genetic variations in genes that encode for nAChRs, particularly those located in the chromosomal region 15q25 (CHRNA5-CHRNA3-CHRNB4 gene cluster), in chromosome 8 (CHRNB3–CHRNA6 gene cluster), and in CHRNA2." (PMID 37626860, 2023).
Alzheimer disease (2 papers, 2025). A progressive, neurodegenerative disease characterized by loss of function and death of nerve cells in several areas of the brain leading to loss of cognitive function such as memory and language. "Additionally, protein tyrosine kinase 2 beta (PTK2B), clusterin, and cholinergic receptor nicotinic alpha 2 (CHRNA2) genes are considered genetic risk factors for late-onset Alzheimer’s disease." (PMID 41007636, 2025).
prostate carcinoma (2 papers, 2016 to 2019). A carcinoma that arises from epithelial cells of the prostate gland. "Notably, one group of genes with very strong negative correlations (≤-0.9) to radiomic features were found to be associated with the AR signaling genes: KLK2, KLK3, HOMER2, BMPR1B, or belong to validated prostate cancer classifiers: CHRNA2, MT1H, DPP4, MYBPC1." (PMID 27438142, 2016).
steatosis (2 papers, 2024 to 2025). Increased lipid within the cytoplasm of cells. "The activation of the cholinergic signaling in the liver through the cholinergic receptor nicotinic alpha 2 subunit (Chrna2) induced the metabolic adaptations to caloric overload and protective mechanisms against steatosis." (PMID 40076796, 2025). "The activation of CHRNA2 coordinates defensive programs against a broad spectrum of MASH-related pathogenesis, including steatosis, inflammation, and fibrosis." (PMID 39028754, 2024).
Stroke (2 papers, 2020 to 2023). Sudden impairment of blood flow to a part of the brain due to occlusion or rupture of an artery to the brain. "Sspo, Shroom3, MuSK, Chrna2, Sorbs2, and Coro6 were upregulated in response to stroke." (PMID 32629989, 2020). "A recent RNAseq study of the TA muscle using a mouse stroke model in 5 m mice found altered transcriptomes compared to age-matched non-stroke mice including: an upregulation in stroke mice >log2fc1 of Gadd45a, Shroom3, Chrna2, and MuSK, along with downregulation (log2fc < −1) of P2ry1." (PMID 37876943, 2023).
benign familial infantile epilepsy (1 paper, 2025). "According to the findings, mutation of the CHRNA2 gene is closely associated with two disorders known as autosomal dominant nocturnal frontal epilepsy (ADNFLE), and benign familial infantile epilepsy (BFIS)." (PMID 39834405, 2025).
depression (1 paper, 2022). "A study on prenatal depression patients found that differentially methylated CHRNA2 related to antidepressant treatment." (PMID 36009493, 2022). "In other words, CHRNA2 was considered to be involved in depression pathogenesis." (PMID 36009493, 2022).
drug dependency (1 paper, 2021). "Chrna2 has been postulated as a candidate gene influencing antisocial drug dependency in adolescence." (PMID 34769161, 2021).
Hypertension (1 paper, 2023). The presence of chronic increased pressure in the systemic arterial system. "Perindopril, a co-target of Chrna2 and Gng7, is an angiotensin-converting enzyme inhibitor indicated for the treatment of hypertension." (PMID 38089628, 2023).
liver disease (1 paper, 2024). "In primary hepatocytes, treatment with the CHRNA2 agonist nicotine suppressed mRNA expression of de novo lipogenesis markers involved in the development of diet-induced liver diseases." (PMID 39028754, 2024). "We then expanded our investigation to explore the potential contribution of non-hepatic CHRNA2 signaling to GAN diet-induced liver disease phenotype and related metabolic dysfunction." (PMID 39028754, 2024).
self-limited familial infantile epilepsy (1 paper, 2024). This syndrome is characterized by the onset of seizures between 3 and 20 months of age (peak 6 months). "In particular, several mutations were found in CHRNA4 and CHRNB2, whereas only four variants were reported in CHRNA2, including one in a family with self-limited familial infantile epilepsy (SeLFIE), previously known as benign familial infantile seizures (BFISs)." (PMID 39596607, 2024).
Tinnitus (1 paper, 2021). Tinnitus is an auditory perception that can be described as the experience of sound, in the ear or in the head, in the absence of external acoustic stimulation. "The Chrna2-cre line could possibly aid in studies of hyperexcitability in T-stellate cells relating to hearing loss and/or tinnitus." (PMID 33563600, 2021).
tumor (3 papers, 2024 to 2025). "Similarly, CHRNA2 upregulation could impact cellular processes such as proliferation, apoptosis, and angiogenesis, influencing both tumor development and the neurological alterations associated with AD33,34." (PMID 41279101, 2025). "Of note, primary PCa tumours showed high JAG1, GP2, GLO1, NPR3, VGLL3, CHRNA2 and SEMA3F mRNA levels in primary PCa tissue samples." (PMID 40219635, 2025). "A four‐mRNA signature (CHRNA2, NPR3, VGLL3 and PAH) was found in primary tumour tissue samples from pN1 PCa patients, and then it was validated using the TCGA‐PRAD and GSE220095 datasets." (PMID 40219635, 2025). "In particular, the expression of the CHRM1, CHRNA2, CHRNA4, CHRNA6, CHRNA7, and CHRNB2 genes was increased in samples from the tissue of the anterior edge of the tumor." (PMID 38393158, 2024).
cancer (2 papers, 2015 to 2026). A tumor composed of atypical neoplastic, often pleomorphic cells that invade other tissues. "In addition, further phage-peptide clones with homology to YBX1, RPL15 and CHRNA2 have been associated with cancer and other disease." (PMID 26039628, 2015).
cardiovascular disease (1 paper, 2023). "Esmolol, which is currently used in the treatment of cardiovascular disease, has been predicted as a co-targeted agent targeting Chrna2 and Gnb3." (PMID 38089628, 2023). "Although no direct association between Chrna2 and cardiovascular disease has been identified, acetylcholine regulates physiological processes in the cardiovascular system." (PMID 38089628, 2023).
psychiatric disorder (1 paper, 2022). A disorder characterized by behavioral and/or psychological abnormalities, often accompanied by physical symptoms. "The position of CHRNA2 in chromosomes (in the 8p region) may be involved in neurodegenerative and psychiatric disorders." (PMID 36009493, 2022).
CHRNA2 also shares sentences with these, for which no sentence is quoted: neurological disorders (2 papers); Seizure (2); alcoholic steatohepatitis (1); breast carcinoma (1); channelopathy (1); colorectal cancer (1); dependence (1); developmental and epileptic encephalopathy (1); Epileptic encephalopathy (1); gastric cancer (1); liver steatosis (1); metabolic disorders (1); type 2 diabetes (1).